CRP (C-reactive protein)
Diseases named in the same sentence as CRP in open-access papers (continued):
Sharing a sentence is not in itself a finding about the gene and the disease.
ischemic stroke (307 papers, 2005 to 2026). A stroke disorder caused by obstruction of blood flow to the brain, due to thrombotic (local blood clot formation) or embolic (due to a blood clot or other material traveling from another site) event. "Elevated serum CRP levels have been shown to be significantly associated with an increased risk of both overall and ischemic stroke." (PMID 40649973, 2025). "Research in a Chinese ischemic stroke cohort linked elevated hs-CRP levels to higher all-cause mortality risk." (PMID 40933377, 2025). "The high levels of CRP in the present study strongly point toward its role as an inflammatory marker related to carotid atherosclerosis, one of the major contributors to ischaemic stroke risk." (PMID 41296388, 2025). "Ongoing trials vary in their inclusion criteria; CASPER, for example, includes ischemic strokes of any cause, as long as CRP is elevated, whereas RIISC‐THETIS requires a ≥30% stenosis in a brain‐supplying artery." (PMID 41182006, 2025). "From a preventive standpoint, chronically elevated CRP is a risk factor for ischemic stroke, analogous to its role in coronary artery disease." (PMID 40869247, 2025). "The concentration of serum CRP exhibits a well-established association with increased susceptibility to coronary heart disease, ischemic stroke, and vascular-related mortality, underscoring its role in inflammatory-mediated vascular pathology." (PMID 40649973, 2025). "Clinically, elevated levels of acute-phase CRP have been consistently linked to larger infarct and poorer neurological outcomes in ischemic stroke, as well as to unfavorable prognoses following intracerebral hemorrhage." (PMID 40649973, 2025). "The aim of this study was to carried out an exploration of the predictive value of serum high-sensitivity C-reactive protein (hs-CRP) plus high levels of lipoprotein-associated phospholipase A2 (Lp-PLA2) for the onset of ischemic stroke (IS)." (PMID 41281270, 2025). "A meta-analysis revealed a log-linear relationship between CRP levels and the risk of death from ischemic stroke in a healthy population." (PMID 39777309, 2024). "In our cohort with mild-to-moderate first-ever ischemic stroke patients, higher levels of baseline hs-CRP were associated with more depressive symptoms over time." (PMID 37848651, 2024). "In our cohort with mild-to-moderate first-ever ischemic stroke patients, hs-CRP levels were associated with more depressive symptoms over time, with an interaction effect for the female sex." (PMID 37848651, 2024). "In our study of mild-to-moderately affected first ischemic stroke patients, we demonstrated that higher baseline hs-CRP levels were associated with more depressive symptoms during a follow-up of three years." (PMID 37848651, 2024). "Raised ferritin and CRP levels in PTB have also been seen to be associated with an increased risk of pulmonary TB-related ischemic stroke." (PMID 39623309, 2024). "During the acute phase of ischemic stroke, hs-CRP in the blood is elevated due to inflammation caused by ischemic brain injury." (PMID 36125980, 2023). "Other molecular mechanisms that are associated with poorer outcomes in febrile ischemic stroke patients include overexpression of intracellular adhesion molecule 1, interleukin 6, tumour necrosis factor alpha, C-reactive protein, glutamate, and more." (PMID 35366212, 2023). "The aim of this study is to evaluate the association of CRP levels during the first 24 h after ischemic stroke with the risk of SHS during the first 30 days after the ischemic stroke, in a real-world, global federated health network." (PMID 37119383, 2023). "Characteristic of the included studies in the meta‐analysis for the between CRP gene polymorphism with the risk of ischemic stroke." (PMID 37221147, 2023).
ischemic stroke (continued). "After PSM, among ischemic stroke patients > 65 years old, CRP levels 1–3 mg/L and > 3 mg/L, were associated with higher risk of early cardiac complications or death (HR 1.11, 95% CI 1.05–1.17 and HR 1.44, 95% CI 1.37–1.51, respectively)." (PMID 37119383, 2023). "A study of 30,239 adults aged ≥45 years from the United States showed that high CRP was positively and significantly associated with incident ischemic stroke." (PMID 37239785, 2023). "The results of this study revealed that positive serum CRP values were associated with ischemic stroke severity and poor prognosis." (PMID 36769677, 2023). "High ratio of C-reactive protein to albumin in individuals with ischemic stroke is associated with an increased risk of HT and poor functional outcomes after thrombolysis." (PMID 36875705, 2023). "In a Cox proportional hazards analysis with patients in level 1 as the reference group, the patients with hs-CRP in level 3 were independently associated with the high risk of ischemic stroke." (PMID 35399841, 2022). "The Framingham study reported that inflammatory markers (such as C-reactive protein, interleukin-6, and fibrinogen) were associated with the risk of ischemic stroke recurrence and transient ischemic attack." (PMID 35756923, 2022). "C-reactive protein (CRP) using a high-sensitivity assay (high-sensitivity CRP, hs-CRP), a low-grade chronic inflammation biomarker, has been demonstrated to be associated with an increased risk of ischemic stroke." (PMID 35399841, 2022). "Ischemic stroke patients with early CRP elevation have an increased risk of death and cardiovascular mortality." (PMID 36079002, 2022). "A meta-analysis of 54 long-term prospective studies indicated that the risk ratio (RR) of per standard deviation higher log(e) CRP was 1.27 (1.15–1.40) for ischemic stroke after adjusting for conventional risk factors." (PMID 35399841, 2022). "Overall, in this prospective study, elevated hs-CRP levels were associated with an increased risk of ischemic stroke among patients with NAFLD." (PMID 35399841, 2022). "The aim of this prospective study was to evaluate the association of hs-CRP with incident ischemic stroke in patients with nonalcoholic fatty liver disease (NAFLD)." (PMID 35399841, 2022). "The objective of this study is to examine the association of hs-CRP levels with the occurrence of ischemic stroke among patients with nonalcoholic fatty liver disease, after adjusting for potential confounding factors." (PMID 35399841, 2022). "High CRP levels are associated with long-term poor functional outcomes in patients with ischemic stroke." (PMID 36079002, 2022). "Elevated CRP levels are associated with an increased risk of future cardiovascular events and unfavorable long-term functional outcomes after ischemic stroke." (PMID 34070731, 2021). "Several studies have shown the association between high CRP values and the increased risk of developing an ischemic stroke." (PMID 34445740, 2021). "A study reports high levels of CRP associated with clinical prognosis in the time window between 12 and 72 hours after ischemic stroke." (PMID 34212039, 2021). "An elevated CRP level has been confirmed as an important risk factor for ischemic stroke, and is associated with greater severity and higher mortality." (PMID 33916503, 2021). "Several studies have reported that higher levels of inflammatory markers such as CRP and IL‐6 are associated with worse outcome after ischemic stroke." (PMID 33314753, 2021). "In univariate analysis, S aureus infection, mitral valve vegetation, higher CRP levels, higher D‐dimer levels, D‐dimer levels ≥3393 μg/L, and vegetation sizes >10 mm were significantly associated with ischemic stroke." (PMID 32017240, 2020). "Elevated levels of CRP are significantly associated with unfavorable long-term functional outcome in patients with ischemic stroke." (PMID 32220241, 2020).
ischemic stroke (continued). "In the Framingham Study, men and women in the highest quartile of CRP levels at baseline had two to three times the risk of ischemic strokes compared to those in the lowest CRP quartile." (PMID 31978079, 2020). "Elevated CRP levels are significantly associated with poor neurological outcomes in patients with ischemic stroke." (PMID 32220241, 2020). "This is in concurrence with a previous report from the Tromsø Study, in which the association between RDW and MI and ischemic stroke was only slightly attenuated after adjustments for C-reactive protein." (PMID 33005859, 2020). "A meta-analysis included the results of 54 prospective studies confirmed that C-reactive protein concentration was associated with the long-term risk of cardiovascular events (including ischemic stroke)." (PMID 33221756, 2020). "In conclusion, higher levels of serum CRP are associated with early depressive symptoms after ischemic stroke." (PMID 31996746, 2020). "While CRP levels in the fourth, or or highest, quartile were an independent risk factor for ischemic stroke, the magnitude of the risk was attenuated when CIMT was added as a covariate to the model." (PMID 31127075, 2019). "C-reactive protein (CRP) is a frequently studied inflammatory biomarker that is implicated in all stages of ischemic stroke." (PMID 30718369, 2019). "The LIMIT study showed that compared with the bottom quartile, subjects with CRP in the top quartile were at increased risk of recurrent ischemic stroke, implying that CRP predicts the occurrence of major vascular events." (PMID 31830923, 2019). "Another prospective population-based study on a Swedish cohort has examined the contribution of 1444C/T polymorphism of the CRP gene for the risk of ischemic stroke and ICH." (PMID 30254628, 2018). "Several prospective studies have reported the association between higher CRP levels and increased disability risk of ischemic stroke." (PMID 29951057, 2018). "A prospective, nested case-control study design from the Physicians’ Health Study cohort demonstrated that none of the single nucleotide polymorphisms related to higher CRP levels showed any association with the risk of incident MI or ischemic stroke." (PMID 29951057, 2018). "High-sensitivity assays that accurately measure levels of CRP have been recommended for use in risk assessment in ischemic stroke patients." (PMID 30254628, 2018). "In the analysis of CRP as a continuous variable, 1 SD (1.69 mg/L) increase in hs-CRP was associated with an 8% higher risk of MI (model 2, HR: 1.08, 95% CI: 1.04–1.12) and an 11% higher risk of ischemic stroke (model 2, HR: 1.11, 95% CI: 1.06–1.16)." (PMID 31249941, 2018). "The 717A > G polymorphism, which is located in the promoter region of the CRP gene, has been associated with ischemic stroke and it was an independent predictor of cerebral ischemia among Chinese population." (PMID 30254628, 2018). "Using a multivariate model including traditional risk factors, CRP levels were found to be significantly associated with ischemic stroke (OR 2.06, 95%CI 1.29–3.29), whilst the 1444C/T polymorphism failed to correlate with ICH." (PMID 30254628, 2018). "RDW was associated with higher risks of MI and ischemic stroke, and these risk estimates were only modestly affected by adjustment for hs-CRP." (PMID 31249941, 2018). "Elevated plasma C-reactive protein levels significantly predict the risk of ischemic stroke and transient ischemic attack." (PMID 28060955, 2017). "Previous meta-analyses suggested that elevated plasma CRP concentration is also positively associated with ischemic stroke risk." (PMID 29245986, 2017). "Genetics variants of CRP gene which were directly associated with circulating CRP level showed significant association with ischemic stroke in a Chinese population." (PMID 27460564, 2016). "Elevation of plasma C-reactive protein, an important inflammatory marker, was known to associate with increased risk of ischemic stroke." (PMID 27460564, 2016).
ischemic stroke (continued). "Our study provided additional genetic evidences to understand the role of HNF1A gene and C-reactive protein underlying ischemic stroke." (PMID 27460564, 2016). "During the acute stage of ischemic stroke, CRP in the blood rises in response to inflammation caused by ischemic brain damage." (PMID 27258004, 2016). "Relatively few studies have corroborated CRP as a risk factor of ischemic stroke, mainly focused on FIS." (PMID 27164124, 2016). "Several studies have reported that higher levels of inflammatory markers such as CRP are associated with worse outcome after ischemic stroke." (PMID 27757207, 2016). "There is increasing evidence that elevated high-sensitivity C-reactive protein (hs-CRP) is a risk factor as well as a prognostic factor for ischemic stroke and coronary events." (PMID 27555819, 2016). "Based on this large population study, CRP concentrations can be used as a clinical screen tool to identify individuals with higher risk of ischemic stroke in Chinese population." (PMID 25191699, 2014). "Previous studies have shown that elevated high-sensitive C-reactive protein (hs-CRP) levels are associated with a 1.27-fold risk for ischemic stroke." (PMID 23356535, 2013). "CRP is a sensitive indicator of active systemic inflammation and an independent risk marker for CV morbidity, including ischaemic stroke." (PMID 24011175, 2013). "A recent study showed that elevated CRP levels in young patients with ischemic stroke were associated with an increased risk of mortality, even 12 years after the CRP measurements." (PMID 24250912, 2013). "The present study also revealed that high CRP (CRP>3) was associated with poor short-term (three months) functional outcome of ischemic stroke." (PMID 24353532, 2013). "It has been shown that increased levels of CRP are associated with a worse outcome in patients with ischemic stroke." (PMID 22132330, 2011). "The association of increased levels of CRP with ischemic stroke has been reported in several clinical studies." (PMID 22132330, 2011). "On the other hand the Framingham study shows that high CRP is associated with a greater risk for ischemic stroke or TIA." (PMID 19400931, 2009). "Additionally, an increase in CRP levels was found to be significantly associated with the occurrence of ischemic stroke (HR: 1.465, CI 1.009–2.127, P = 0.05)." (PMID 38167529, 2024). "We aimed to assess whether elevated baseline levels of high-sensitivity C-reactive protein (hs-CRP) are associated with depressive symptoms over time in a prospective cohort of mild-to-moderate first-ever ischemic stroke patients." (PMID 37848651, 2024). "A C-reactive protein level of 10.25mg/L is linked to a severe ischemic stroke." (PMID 40092874, 2024). "IL-6 is the main driver of the production of the pro-inflammatory cytokine of CRP production in the liver, which is associated with an increased risk of ischemic stroke and is involved in the process of ischemic brain injury by binding to IL-6R to initiate intracellular signaling." (PMID 38104193, 2023). "Summary estimates for the between CRP gene polymorphism with the risk of ischemic stroke." (PMID 37221147, 2023). "However, the association between CRP single nucleotide polymorphisms (SNPs) (rs1800947, rs1130864, rs3093059, rs2794521, and rs1205) and ischemic stroke is still debatable." (PMID 37221147, 2023). "High CRP levels may reflect the progression of vascular disease and may be associated with poor neurological outcomes in patients with ischemic stroke." (PMID 36079002, 2022). "This present study provided evidence that NAFLD might be associated with an increased risk of ischemic stroke by elevating hs-CRP levels." (PMID 35399841, 2022). "It was observed that the post-procedure serum levels of C-reactive protein were associated with the fibrin content in clots, and therefore could be used to indirectly predict fibrin-rich clots in ischemic stroke patients." (PMID 36297588, 2022).
ischemic stroke (continued). "In addition, the Emerging Risk Factors Collaboration22 also defined an increase in relative risk of CHD and ischaemic stroke associated with CRP." (PMID 35118716, 2022). "Besides association with cancers, it was previously reported that elevation of CRP levels was associated with increased risk of ischemic stroke." (PMID 35109885, 2022). "CRP was associated with mortality (HR 1.40, CI 1.01, 1.96, p = 0.046), and neopterin was associated with the combined endpoint (recurrent ischemic stroke or death) (HR 1.52, CI 1.06, 2.20, p = 0.023), adjusted for age, sex, prior cerebrovascular disease, modified Rankin Scale, and creatinine." (PMID 34879833, 2021). "Thus, this study assessed plasma levels of LPS, LBP, LTA, and CRP in patients with different causes of ischemic stroke, intracerebral hemorrhage (ICH) and transient ischemic attacks (TIAs) compared to controls." (PMID 33753837, 2021). "In addition, several studies have shown that CRP measurements at different time points are associated with the prognosis of patients with ischemic stroke." (PMID 32220241, 2020). "The results of marker discovery studies on plasma of ischemic patients presented markers, such as BNP, von Willebrand factor, ICAM-1, CRP, and interleukin-6, through biomarker research progress associated with causes of ischemic stroke, which differed from the biomarkers identified in our study." (PMID 32466277, 2020). "Elevated CRP level is independently associated with the excessive risk of ischemic stroke." (PMID 30718369, 2019). "Elevated C-reactive protein levels were associated with ischemic stroke in a meta-analysis." (PMID 29494700, 2018). "RDW mediated 7.2% (95% CI: 4.0–30.8%) of the association between hs-CRP and ischemic stroke." (PMID 31249941, 2018). "In addition, genetic studies have indicated a significantly association between CRP gene mutation and the risk of ischemic stroke." (PMID 29245986, 2017). "Given the broad effects of inflammation, interplay between CRP and conventional risk factors of ischemic stroke would cause confounding biases which might explain the inconclusive and controversial role of CRP underlying ischemic stroke in previous studies." (PMID 27460564, 2016). "As CRP is mainly synthesized in liver by hepatocytes, the HNF1A gene might be an important regulator of CRP and associate with ischemic stroke through its regulatory effects on CRP." (PMID 27460564, 2016). "In recent years, studies in general populations observed association of CRP with ischemic stroke." (PMID 27460564, 2016). "Thus, associations between plasma CRP and short-term clinical outcomes after ischemic stroke should be further validated in other cohorts." (PMID 27258004, 2016). "Indeed, genetic variants of CRP gene were identified for their contribution to both CRP level and susceptibility of ischemic stroke." (PMID 27460564, 2016). "In addition, in our previous study we found that complement activation and elevated CRP levels were independently associated with the clinical severity and different outcome measures of ischemic stroke, indicating their additive effect." (PMID 22206485, 2011). "It has been established that C-reactive protein levels can reflect the extent of cerebral infarction, and elevated levels of C-reactive protein are associated with increased in-hospital mortality as well as long-term poor functional outcomes in patients with ischemic stroke." (PMID 36875705, 2023). "Due to its low-cost and standardized measurement, CRP measurement can be used universally, even in settings of restricted resources and provide valuable information for the treating physician to identify those at high-risk of major cardiac complication related to ischemic stroke." (PMID 37119383, 2023). "In addition to CRP gene, circulating CRP level was associated with some regulatory genes that could also be considered as candidate genes of ischemic stroke." (PMID 27460564, 2016).